CCL19 (C-C motif chemokine ligand 19)
Diseases named in the same sentence as CCL19 in open-access papers (continued):
Sharing a sentence is not in itself a finding about the gene and the disease.
infection (continued). "To define the specific pathways downstream of the chemokine receptor important for HIV integration, we next tested inhibitors of p38, MEK1/ERK1/2, JNK, AP-1 and NF-κB, prior to infection of CCL19-treated resting CD4+ T cells." (PMID 27459960, 2016). "The establishment of latency in vitro through direct infection of resting CD4+ T-cells is significantly enhanced by CCL19 and mDC, but the efficiency is dependent on virus titre, co-receptor usage and there is significant donor variability." (PMID 27383184, 2016). "We show that the establishment of latency in vitro through direct infection of resting CD4+ T-cells is significantly enhanced by CCL19 and mDC, but the efficiency was dependent on virus titre, co-receptor usage and there was significant donor variability." (PMID 27383184, 2016). "The establishment of latency in vitro through direct infection of resting CD4+ T-cells is significantly enhanced by CCL19 and mDC, but the efficiency was dependent on virus titre, co-receptor usage and there was significant donor variability." (PMID 27383184, 2016). "In these experiments, three experienced scientists performed these experiments using multiple different donors and each found similar results–that roughly half of the donors required the presence of CCL19 to facilitate infection of resting CD4+ T-cells." (PMID 27383184, 2016). "For instance, upon infection, the reactivated T cells will secrete abundant IFN-r, which will induce the down-regulated expressions of CCL21 and CCL19, and thereby down-regulate the immune response of T cells upon the next infection." (PMID 26161081, 2015). "These cells were either left untreated or were treated with the cytokine IL-7 or the chemokine CCL19 for 72 h prior to infection." (PMID 26067822, 2015). "Treating resting CD4+ T cells with CCL19 increased productive infection 2-fold over untreated cells, while IL-7 treatment produced a 5-fold increase in productive infection." (PMID 26067822, 2015). "If these findings reflect that CCL19 and CCL21 not only carry out their homeostatic role, but also play a pathogenic role in these infections, this should be examined in forthcoming studies." (PMID 24507453, 2014). "In contrast, expression of the B cell, T cell and DC chemoattractants CCL19 and CCL21 increased progressively to 7 days post infection with CCL19 elevated at day 1 and rising before CCL21." (PMID 24847941, 2014). "The T cell chemoattractants CXCL9, CXCL10 and CCL19 are significantly elevated in serum during the acute infection but largely return to normal levels following treatment, resolution of the erythema migrans and recovery." (PMID 24740099, 2014). "At late phase of infection, high expression of both CCL19 and CXCL12 was observed only in control mice and correlated with the maintenance and the lymphoid organization of immune infiltrates composed of CD4+ and CD8+ T cells, macrophages, DC and FDC." (PMID 23717393, 2013). "We also evaluated replicate samples to investigate if the profile of CCR7 mRNA and protein expression correlated with the ability of MDDC to migrate to a CCL19 concentration gradient, measured 48 h post-infection (n = 5 donors)." (PMID 21731495, 2011). "Following infection of CCL19-treated CD4+ T-cells with NL4.3 with enhanced green fluorescent protein (EGFP) inserted into the nef open reading frame (NL4.3- Δnef-EGFP), there was no EGFP expression detected." (PMID 21992606, 2011). "The lack of mDC accumulation in lymph nodes despite evidence for enhanced CCR7/CCL19-mediated recruitment in progressive infection led us to suspect that lymph node mDC were dying at an increased rate in these tissues." (PMID 21203477, 2010). "Prior to infection, we verified that CCL19-treated CD4 + T cells exhibited minimal expression of CD69 and CD25, confirming a resting phenotype, whereas cells treated with phytohaemagglutinin (PHA) and interleukin-2 (IL-2) for 24 hours showed robust upregulation of both markers." (PMID 40372991, 2025).
infection (continued). "Furthermore, genes involved in immunity and infection [e.g., chemokine ligand 19 (ccl19), dedicator of cytokinesis 8 (DOCK8), and intercellular adhesion molecule-1 (ICAM-1)] were also significantly dysregulated." (PMID 36984847, 2023). "Levels of 3 mediators, CXCL11, CCL19, and IL-21, were higher in patients whose symptoms resolved after antibiotic therapy, implying that they might play a protective role in the infection and contribute to symptom resolution." (PMID 37209716, 2023). "CCL19 plays a crucial role in the immune system’s response to inflammation and infection." (PMID 37443817, 2023). "Moreover, the infection of 16-week-old Ccl19-iEYFP Ltbrfl/fl mice (Dox off 8 wk) with C. rodentium revealed increased susceptibility of the mice when LTβR signaling was abrogated specifically in adult Ccl19-expressing FRCs." (PMID 35440118, 2022). "However, from 36 h post-IBDV-infection, the pEGFP-N1/CCL19 plasmids strongly inhibit the gene expressions of both IBDV VP1 and VP2." (PMID 35935208, 2022). "Therefore, we next assessed B cell- and DC-mediated HIV-1BaLtrans infection of TN treated with the chemokine CCL-19." (PMID 33688006, 2021). "Preference of SPARC for CCL19 may suggest a mechanism to avoid receptor desensitization away from sites of infection and to facilitate some degree of desensitization near sites of infection." (PMID 33633185, 2021). "In addition, TN infection with a CCR5-tropic virus appears to occur in the presence of CCL19 and B cells." (PMID 33055422, 2020). "This hypothesis is further strengthened by the observation that decreased migration capability occurred already 4 hpi, while the chemokine receptor CCR7, mediating CCL19-directed migration, was downregulated at later time points post infection." (PMID 31963276, 2020). "Next, we found increased mRNA expression and activity levels of Arg1, mRNA expression of Fizz, Chi3l3, Cd209d, Cd209e, Mrc2 (Cd206), Marco, Il13, Saa1 (Serum amyloid A1 protein), Ccl17, Ccl19, Ccl20, Ccl22, and Ccl24 in Stat2−/− mice compared to WT mice during super-infection." (PMID 30337919, 2018). "The expression levels of CCL19 were constant during all stages of infection." (PMID 28038465, 2017). "Resting CD4+ T-cells, with or without CCL19, were not susceptible to infection using virus stocks with a TCID50 <0.5, as measured by lack of integration and low RT." (PMID 27383184, 2016). "These ligands could then potentially activate the relevant chemokine receptors and signalling pathways, similar to the effect of CCL19, to enable infection as we and others have previously shown." (PMID 27383184, 2016). "Therefore several exogenous signals, including CCL19 and mDC, can facilitate the efficient, direct infection of resting CD4+ T-cells and establishment of latency." (PMID 27383184, 2016). "Latent infection increased by 3-fold after treatment with either CCL19 or IL-7." (PMID 26067822, 2015). "The higher level of CCL19 in TB patients could be due to active infection where a number of crucial cells including macrophages and T cells are recruited to contain infection." (PMID 24885723, 2014). "Moreover, in experimental murine R. conorii infection increased expression of CCL19 and CCR7 and in particular, CCL21 was associated with lethal infection." (PMID 24507453, 2014). "We next tested whether infection of skin DCs was likely to have an impact on their capacity to migrate towards the chemokine CCL19, which is expressed in the T cell zones of LN follicles to attract CCR7-expessing migratory cells." (PMID 25474532, 2014). "Increased CXCL13 expression from day 1 post infection preceded increased CCL19 and CCL21." (PMID 24847941, 2014). "Finally, following infection with NL4.3Δnef/EGFP of CCL19-treated and IL-2-PHA activated CD4+ T-cells, EGFP expression was 0% and 2% respectively (n = 1)." (PMID 21992606, 2011).
infection (continued). "Infection with HTLV-1A/CoI-L resulted in low overall frequency of monocytes, DCs, and neutrophils producing IL-10, with elevated frequencies of those producing TNF-α in both compartments, linked to high expression of IL-6, CCL2, and IL-33 in blood and of MMP1, IL-1β, CCL3, and CCL19 in the lung." (PMID 41006234, 2025). "Notably, CCL19 showed downregulation at 72 h post-infection." (PMID 41305370, 2025). "Moreover, expression of chemokines associated with the homing of lymphocytes to the infected lung such as CXCL13 and CCL19 was significantly lower in males compared to females, further indicating that B cell follicle formation in response to H37Rv infection is impaired in males." (PMID 32198367, 2020). "Therefore, levels of CXCR3 (receptor for CXCL9 and CXCL10), CXCR5 (receptor for CXCL13), CCR5 (receptor for CCL3 and CCL5), and CCR7 (receptor for CCL19) were analyzed on CD45hiCD11bloCD19+ B cells which infiltrated the brain at 7, 14, 30, and 60 days post infection." (PMID 27207308, 2016). "Thus, at early stage of infection high levels of CCL19 in IRF-8−/− mice may account for the pulmonary recruitment of immune infiltrates, possible through a chemokine/lymphotoxin loop." (PMID 23717393, 2013). "Thus, iBALT formation is complex and modulation in the levels of factors such as SDF-1α/CXCL12, CD30L/CD153 and MIP-3β/CCL19 by M3 may contribute to the formation of iBALT in context of MHV-68 infection in wood mice." (PMID 21445235, 2011). "CCL19 induces terminal activation of DC and promotes DC production of proinflammatory cytokines within lymph nodes, although this effect would not explain the finding of increased responsiveness of mDC in animals with stable infection that had normal levels of CCL19 in our study." (PMID 21203477, 2010). "At 24 h post-footpad infection with LCMV, naive lymphocyte entry to CCL19−/− inflamed pLNs was more dependent on EBI2." (PMID 39708807, 2025). "When we performed short-term transfers, pLNs from mice given CCL19 showed EBI2−/− B cells homing at nearly the same level as WT-transferred B cells, thus reversing the effect of infection-induced CCL21 downregulation." (PMID 39708807, 2025). "Genetic ablation of Il33 expression in Ccl19-Cre+ cells results in the reduction of virus-specific CD8+ T cells that produce IFN-γ and TNF during LCMV clone 13 infection." (PMID 38038708, 2024). "CXCL13 and CCL19 mRNAs at these times were then measured by RT-qPCR, and throughout RVFV MP12 infection, relative expression (normalized to GAPDH) of these chemokines continued to increase, suggesting progressive activation of the noncanonical NFκB pathway." (PMID 37515252, 2023). "During active infection, the dendritic cells' expression of CCR7, a receptor for the chemokines CCL19 and CCL21, is increased." (PMID 35722038, 2022). "The CCL19 and CCL4 genes showed a similar trend, and they all peaked at 6 h (p < 0.05) and then decreased after infection and immunization." (PMID 36363767, 2022). "At later time points during infection, HSV-2 further downregulates chemokine receptor expression of CCR7, recognizing the lymphoid tissue expressed chemokine CCL19." (PMID 31963276, 2020). "In contrast, HRSV and HMPV infections induce less CCR7 expression and less efficient DC migration in response to CCL19 than HPIV3." (PMID 31632965, 2019). "Using RT-qPCR, we found a significant increase in the gingival expression of CCL19 and CCL21 of WT upon infection." (PMID 29967614, 2018). "Binding of HIV gp120 to CXCR4 and CCL19 to its receptor CCR7 activate intracellular signalling that alters actin dynamics, facilitating nuclear localisation and infection of resting T-cells." (PMID 27383184, 2016). "Expression of the B cell chemoattractants CXCL13, CCL19 and CCL21 increased progressively post infection." (PMID 24847941, 2014). "The expression of CCL13, CCL19 and CXCL1 was significantly higher in cells infected with the Mtb:Δ-sigH mutant relative to Mtb or Mtb:Δ-sigH:CO at 24 hrs post-infection." (PMID 22235255, 2012).
infection (continued). "The mean fold increase of US RNA (expression at day 4 compared to day 0) following infection of PHA/IL-2 activated, CCL19-treated and unactivated CD4+ T-cells was 21.1, 1.1 and 0.5 fold respectively (n = 5; p < 0.05 for all comparisons)." (PMID 21992606, 2011). "Upregulation of the expression of adiponectin, CCL19, and CCL17 genes following infection with either of the ILTV strains in the TOCs in this study indicates that gG may not influence the transcription of these genes locally in the trachea." (PMID 39804092, 2025). "Hypothetically, these chemokines may contribute to TB control by attracting monocytes to the site of infection via CCL2 and antigen-engaged B cells and central memory T cells via CCL19 and CCL21, respectively." (PMID 40458184, 2025). "Since CXCL13 and CCL19 have been shown to be transcribed specifically during activation of the noncanonical NFκB pathway, mRNAs of these chemokines were measured at multiple timepoints following RVFV MP12 infection." (PMID 37515252, 2023). "Since CCL19 and CCL21 are the unique ligands for CCR7, contributing to DC migration into the dLN, we treated mice with CCL19- and CCL21-neutralizing Abs prior to infection and subsequently measured bacterial burdens in dLN." (PMID 36618364, 2022). "Obviously, there were more IBDV-positive cells in the empty vector negative control group and those of the pEGFP-N1/CCL19 group at 24, 48, and 72 h post-infection." (PMID 35935208, 2022). "Prior studies have shown that TN can be infected in vitro with CXCR4-tropic HIV-1 when pretreated with the chemokine CCL-19, the ligand for the CCR7 receptor, expression of which significantly increases during the acute phase of infection when the latent reservoir is established." (PMID 33688006, 2021). "Unexpectedly, we found a significant increase in CCL19 plasma levels during infection that was absent in ICI-treated patients." (PMID 34407944, 2021). "However, later during infection, HSV-1 and HSV-2 also hamper CCR7 expression as an additional counterstrike for delaying mDC migration toward the SLO-expressed chemokine CCL19." (PMID 31963276, 2020). "Instead, transcripts for CCR7, the receptor for CCL19 and CCL21, were significantly lower in males compared to females in the late stage of HN878 infection, indicating reduced recruitment of DCs and/or T cells to the site of infection." (PMID 32198367, 2020). "To further confirm the residency nature of most of the cervical cells supporting infection, we stimulated 10 day-infected tissue blocks with CCL19, CCL21, and S1P overnight to attract non-TRM out of the tissue in a transwell migration assay." (PMID 31628331, 2019). "Similarly, CCL19, CCL22, and CXCL13 were significantly upregulated by a primary infection in the R line of the HSF flock when compared to its S line counterparts." (PMID 30678719, 2019). "Indeed in mouse lymphoid tissue specifically the homeostatic chemokines CCL19, CCL21 and CXCL13 were downregulated after infection with several different pathogens leading to altered homing, positioning and priming of lymphocytes within the LN61." (PMID 29379035, 2018). "Indeed, HCMV impairs mDC transwell migration capability following a CCL19-chemokine gradient, despite equivalent expression levels of the cognate chemokine receptor CCR7 at the corresponding time points post-infection." (PMID 28484459, 2017). "Differential changes in the expression of CCL19, CCL20, IL-8, IL-15, and Trail/TNF (ligand) superfamily members TNFSF10 and TNFSF15 in DT40 cells were also observed at different time points after vvIBDV infection." (PMID 28086922, 2017). "In fact, upon infection the induced-expression of CXCL13 together with other chemokines, such as CCL21 and CCL19, could be indispensable to induce ectopic GC development." (PMID 26771137, 2016). "It is unclear why resting CD4+ T-cells from some, but not all, donors are permissive to direct infection without CCL19." (PMID 27383184, 2016).
infection (continued). "One group described that infection of resting CD4+ T-cells was possible without CCL19 in all donors." (PMID 27383184, 2016). "To do this, we cultured untreated resting CD4+T cells or prestimulated the cells for 3 days with IL-7, CCL19, or CD3/28 beads and then spinoculated the cells with HIV, after which we measured the ratio of integrated to total HIV DNA 48 hours post infection." (PMID 22911005, 2012). "In any case, results of this study have clearly demonstrated that upon MVA-B infection, bystander and viable MDDC are able to capture HIV antigens and, after full maturation, are able to migrate toward a gradient of CCL19 and CCL21, thus they would be competent to reach secondary lymphoid organs." (PMID 21625608, 2011). "We excluded patients with clinical signs of infection, and found that among all of the studied chemokines it is only CCL19 (also previously known as Macrophage Inflammatory Protein-3β i.e. MIP-3β) of which levels were significantly lowered in women with preterm delivery." (PMID 17570169, 2007). "During infection, the clearance rates of pathogens is gradually accelerated, and the outcome is similar to that of the CCL19 + HBV group, which may be related to the compensatory production of CCL19 in the tissues, and mediating immune activation." (PMID 34218330, 2021). "A positive correlation between MIG/CXCL9, IP-10/CXCL10, I-TAC/CXCL11 and MIP-3β/CCL19 and mononuclear cell infiltrates was also observed in previous studies on TBE patients, confirming their potential involvement in lymphocyte extravasation to the site of infection during TBE." (PMID 34277474, 2021). "Together, interactions among multiple molecules consisting of this network, such as CD19, CD 22, and CD79A/B, and chemokines including CCL19, CCL22, and CXCL13 may contribute to enhanced immune responses in the resistant line in the HSF flock to the innate infection." (PMID 30678719, 2019). "While there is evidence that upon DC activation and infection, chemokines are important to mediate T cell repositioning to DCs, our data suggests that chemokines CCL19/21 that bind to CCR7 do not play a role in T cell positioning to DCs in the absence of infection." (PMID 30093900, 2018). "Despite previous studies showing that unstimulated and CCL19-treated resting CD4+ T-cells lack activation markers that are required for productive infection, one important issue we aimed to address in these experiments was whether there was low level productive infection in this model." (PMID 27383184, 2016). "Interestingly, CCL19 treatment of resting CD4+ T cells produced 0.2% reactivatable provirus from the isolated uninfected cell population, while the initial latent cell population after infection was 0.47%." (PMID 26067822, 2015). "The absence of productive infection was further confirmed by staining for intracellular p24 expression where we found that CCL19-treated infected CD4+ T-cells resulted in <1% p24-positive cells in contrast to IL-2/PHA activated infected CD4+ T-cells (mean p24 expression ~6-9%; n = 2)." (PMID 21992606, 2011). "After infection with HIV-1 at 1 multiplicity of infection (MOI), the cells were cultured in the absence of cytokines, but with CCL19 to sustain cell survival and establish latent HIV infections." (PMID 36742330, 2023). "In contrast, the frequencies of CD3+TCRαβ−CCR7+ and CD3+TCRαβ+CCR7+ MDMs were higher than that of CD3−CCR7+ MDMs (asterisks), and CCL19 levels (ligand to CCR7) were not modified as a result of H37Ra and H37Rv infection." (PMID 35008755, 2021). "On the other hand, there was no distinct trend between infection with CVI988 and vvRB1B and the expression of cytokines and chemokines, such as IL-10, IFN-γ, STAT1, IRF1, CCL19, and CCL26." (PMID 32210095, 2020). "After 2 h of migration without chemokine as well as toward CCL19 or CXCL12, cells in the lower well were counted and infection efficiency was determined before and after migration." (PMID 28484459, 2017).